CD33 (CD33 molecule)
Diseases named in the same sentence as CD33 in open-access papers (continued):
Sharing a sentence is not in itself a finding about the gene and the disease.
tumor (continued). "In AML, where on-target off-tumor effects have been observed in single-target CD33 or CD123 CAR-T cell therapies, CD33-/CD123-bispecific CAR-T therapies have been designed to achieve more precise targeting." (PMID 39844819, 2025). "The clinical application of CD33- and CD123-targeting CAR-T cells has been limited due to their on-target off-tumor toxicity against hematopoietic stem cells (HSCs) and normal tissues." (PMID 40474230, 2025). "In vivo and in vitro experiments have demonstrated that this system can continuously release fully humanized anti-CD33-anti-CD3 bispecific antibody (bsAb), efficiently redirecting CD3+ T lymphocytes to CD33+ AML mother cells for exerting anti-tumor effects." (PMID 40458695, 2025). "Seven patients in the testing group exhibited lymphatic tumor emboli in primary cancer, and these patients displayed decreased CD3+CD8+ cells and increased CD11b+CD14+/CD33+CD14+ M‐MDSC levels." (PMID 39749673, 2025). "Treatment with [225Ac]Macropa-PEG4-7065 in Nomo-1 and PDX AML disseminated models delayed tumor growth and improved overall survival compared to controls, including [225Ac]DOTA-anti-CD33, a clinical stage-radioimmunotherapy under evaluation in AML." (PMID 41282197, 2025). "In contrast, Allo15CAR33-NKT cells demonstrated cytotoxicity against both CD33+ and CD33- AML tumor cells, indicating they can target tumor cells through both CAR33-dependent and independent mechanisms." (PMID 39893165, 2025). "To accurately characterize tumor cells within the HGSC microenvironment, we applied a stringent gating strategy to exclude immune (CD45+, CD33+, CD14+) and stromal (CD90+, CD140a+) components." (PMID 40877861, 2025). "Immunohistochemically, the tumor cells commonly express CD117, mast cell tryptase, CD13, CD33, CD43, and CD68." (PMID 39404971, 2024). "While our study was small, it clearly demonstrated anti-tumor activity of AMV564, a novel bispecific TandAb against CD33+ AML and AML cell lines in vitro and in vivo." (PMID 38696390, 2024). "One of these approaches consists of deleting CAR-T targets, like CLL-1 or CD33, with CRISPR/Cas9 from HSCs prior to transplant, thus avoiding off-tumor effects from CAR-T therapy and restricting the cytotoxic effect of CAR-T cells just to AML cells." (PMID 38694825, 2024). "Here we summarize the top seven most correlated SIGLECs in the tumor sample: SIGLEC-1,5,7,9,10,11 and CD33, meaning a single SIGLEC can represent a majority of another, so that they are less independent." (PMID 38650859, 2024). "Similar observations were made using a CD33 targeting TCB with AML cell lines and primary AML cells showing that enhanced tumor cell killing by the combination of Ven/Aza and TCBs is tumor target independent." (PMID 38212534, 2024). "Over the course of our analysis of the M-MDCSs, defined as CD45+ LINneg (CD3, CD56, CD19) CD11b+CD33+CD14+HLA-DRdim/neg, in pts with CRC, we observed a significant increase in CD15+ monocytes in both the PB and tumor tissue." (PMID 39126041, 2024). "Irrespective of the treatment, T cells were the predominant immune cell population in the tumor in JIMT-1 and MDA-MB-231 mice, whereas CD33+ myeloid cells constituted the most prevalent population in MCF-7 tumors." (PMID 38742103, 2024). "We first compared the anti-tumor activity of CD33 CAR T cells against AML and B-ALL cell lines that were engineered to express equivalent levels of CD33 (U937CD33 and Nalm6CD33)." (PMID 39039086, 2024). "The combinatorial use of 1 nM CD33 Db-FM and 1 nM CD117 Db-FM resulted in a significant increase in overall tumor cell lysis." (PMID 39294295, 2024). "Based on this, we designed CD33 CARKR to avoid CAR ubiquitination, which enhanced the activation and anti-tumor activity of CAR-T cells in vitro experiments." (PMID 38184596, 2024).
tumor (continued). "Next, we treated tumor-bearing mice with AdFITC-CAR T-cells and either 12.5 μg CD117 or CD33 Db-FM as monotherapies or a combination of both adaptors for three weeks starting from seven days after MOLM14-CD117highGFP+Luc+ injection." (PMID 39294295, 2024). "Following immunotherapy, tissue samples from all HP patients exhibited tumor infiltration by M2-like CD163+, CD33+, PD-L1+ luster-forming epithelioid macrophages and enrichment of TAM." (PMID 39034998, 2024). "LTB4 from CAF-activated CD33+ MDSCs stimulated BLT2 signaling in tumor cells, enhancing tumor stemness." (PMID 38786066, 2024). "Additionally, there is evidence indicating that CD33 may contribute to anti-tumor immune responses." (PMID 38742049, 2024). "The markers used to characterize the immune and tumor compartments of the iTME were: CD3, CD4, CD8a, FOXP3, PD-1, PD-L1, CD68, CD33, and pan-keratin (PanCK)." (PMID 38898200, 2024). "In a Nomo1 cell line xenograft mouse model implanted in NSG mice, we again noted improved tumor control over empty CAR T cells as well as similar efficacy of aITGB2 CAR T cells and anti-CD33 CAR T cells." (PMID 37904046, 2023). "We found that at a 1:1 effector-to-tumor (E:T) ratio, aITGB2 CAR T cells showed levels of proliferation and cytotoxicity that were similar to those observed with anti-CD33 CAR T cells." (PMID 37904046, 2023). "The inferred MIF signaling network further revealed that tumor cells and CAFs are prominent sources of MIF ligands acting on MDSCs (CD33+CD11b+HLA-DRlo), monocytes or macrophages and DCs." (PMID 36878933, 2023). "The most important tumor antigens targeted by NbCAR-T cells against B cell malignancies include CD19, CD22, CD20, CD33, and CD72." (PMID 36761751, 2023). "In a mouse model of AML, anti-CD33 CAR-T cells prevented tumor growth, leading to significantly prolonged survival, although each mouse eventually developed a tumor." (PMID 37296906, 2023). "For hematologic malignancies, CD33 and CLEC12A (AML), BCMA, and CD38 (MM), and CD30 (PTCL) are targeted as tumor arms." (PMID 36830717, 2023). "RevCAR-modified and RevTM-redirected T cells were highly effective in eliminating various cancer cells expressing different TAAs in vitro and using mouse tumor models, including patient-derived AML cells expressing CD33 and CD123 and glioblastoma cells." (PMID 36922828, 2023). "Strikingly, when analyzing the immunophenotype of tumor cells within this cluster, an upward trend in the expression levels of CD19, CD34, CD24, CD20, nuTdT, cyMPO, and CD33 was recorded." (PMID 38250553, 2023). "In both models, we saw marked elimination of human CD45+ cells as well as decreased spleen size in mice treated with aITGB2 or CD33 CAR T cells, with prominent outgrowth of tumor cells in empty control." (PMID 37904046, 2023). "CD33 is also present in MDSC; so, targeting CD33 will mediate anti-tumor activity through direct cytotoxicity of CD33+ blasts and also through inhibition of CD33+ MDSCs." (PMID 37345050, 2023). "A compound CAR targeting CLL1 and CD33 was constructed and allennimumab was used to clear CAR-T cells after tumor eradication." (PMID 36523990, 2022). "Data suggest a dual anti-tumor effect of AMG 330 through increased T-cell mediated cytotoxicity against AML blasts and CD33+ MDSC." (PMID 36304465, 2022). "We previously reported that a peculiar population of tumor-infiltrating macrophages, characterized by the co-expression of CD163, CD33 and PD-L1, was present in the tumor microenvironment of HPD patients." (PMID 36555441, 2022). "While there has been some success in early trials targeting CD33 and CD123, on-target off-tumor toxicity has been of concern." (PMID 35681175, 2022). "Examining CoMMpass data, we confirmed both CD33 and PTPRC transcripts to be significantly increased at first relapse vs. diagnosis in patient tumor cells." (PMID 35840578, 2022).
tumor (continued). "Due to the presence of CD33 in normal myeloid progenitors, CD33-CAR T not only clear out tumor cells, but also wipe out myeloid progenitors, resulting in on-target off-tumor side effects, which explained the failure of CD33-CAR T clinical trials." (PMID 37193354, 2022). "CD33 and CD123 are highly expressed by AML blasts and pre-clinical models have demonstrated CD33 and CD123 directed CAR T cells have highly potent anti-tumor activity." (PMID 35740430, 2022). "Given the flexibility of the RevCAR system to target different tumor entities by easily replacing RevTMs with different specificities, a combinatorial gated approach could be established and successfully used to target CD33 or CD123 on the surface of patient-derived AML blasts." (PMID 34638268, 2021). "GTB-3550 is a novel CD16/IL-15/CD33 TriKE that induces natural killer cell function by targeting malignant cells as well as the CD33+ MDSC, which contribute to tumor-induced immunosuppression." (PMID 34521810, 2021). "Heatmaps show enrichment scores (NES) of GO pathways in primary tumors and LN metastases according to NE-low and NE-high phenotype, CD68+, CD163+, CD33+ cellular densities and MHCII-expression in tumor cells (in brief: macrophage-related parameters)." (PMID 34200100, 2021). "The reported in vivo and in vitro results of assessing the CD33-CAR T cells were the significant proliferation of CAR T cell, prominent anti-tumor activity, increased level of cytokine production, degranulation, and leukemia burden reduction." (PMID 34412685, 2021). "Regarding the CD33 antigen, significant differences in expression were detected between the normal control and CRC samples for both cancer cells and the tumor stroma (p < 0.0001, respectively)." (PMID 33625532, 2021). "Antibodies targeting tumor antigens (anti-BAFF-R, anti-CD123, anti-CD157, anti-SLAMF7, anti-GD2, anti-CD33) with an enhanced affinity toward CD16, which further increases ADCC efficacy, were evaluated in multiple clinical trials." (PMID 34203935, 2021). "In conclusion, it is inferred that the probability of CD33-directed CAR-T triggering “on-target, off-tumor toxicity” is lower than that of CD123- and CLEC12A-directed CAR-T cells." (PMID 34975912, 2021). "BiKEs and TriKEs designed to engage tumor antigens (e.g., CD19, CD20 for B cell NHL; CD33 and CD123 for AML; CD30 for HL), and CD16 receptor facilitate NK cell immunological synapse formation." (PMID 34203935, 2021). "First, second and third generation CAR NK cells have been generated, using lentiviral vectors, to target tumor antigens such as CD19, CD20, CD33, CD7, CD22, ErbB2 and EGFR." (PMID 33450862, 2021). "In this context, the surface antigen CD33, which is stably expressed on leukemic blasts in AML and a subset of pediatric ALL provides a potentially useful tumor target." (PMID 34398302, 2021). "The frequency of human myeloid cells defined by the expression of either CD33, CD11b or CD11c in CD3, CD19-negative, hCD45+ cells was higher in tumor tissue as compared to bone marrow." (PMID 33148223, 2020). "MDSCs constituted about 5% of the cells within GBM tumor masses and where depicted with obvious CD33+/CD15−/CD14−/HLA-DR− negative lineage subsequent to CD33+/CD15+/CD14−/HLA-DR− neutrophilic as well as CD33+/CD15−/CD14+/HLA-DR− monocytic subtypes." (PMID 33204365, 2020). "We further found that the direct CD33+CD11b+HLA-DR− MDSC induction and tumour-derived MDSC induction in vitro were decreased in the absence of METTL3." (PMID 33059689, 2020). "The MDSC populations were marked as eMDSC (Lineage–CD11b+CD33+), amounting at 0.06%, and as PMN-MDSC (CD45+CD15+CD14–CD11b+), amounting at 0.11% of the total tumor cell suspension in GCT." (PMID 32814714, 2020). "CAR-NK cells have been tested for tumor antigens (CD19, HER2, CD33, CD7, MUCI, and NR) and SARS-CoV-2 infected cells." (PMID 32731404, 2020).
tumor (continued). "Various CARs have been engineered into NK-92 cells to kill specifically CD19, EpCAM, or CD33-positive tumor cells, and these CAR-NK cells have shown high anti-tumor effects." (PMID 33193399, 2020). "They further observed elevated levels of CD33+ MDSC levels at recurrence correlated with overall survival, whereas infiltration of MDSCs into the tumor microenvironment correlated with poor prognosis." (PMID 33204365, 2020). "The number of CD33+ cells was positively correlated with the expression of METTL3 in tumour cells (R = 0.145, P = 0.041) and tumour-infiltrating immune cells (R = 0.182, P = 0.011)." (PMID 33059689, 2020). "This study demonstrated that CD33+MDSCs numbers and YAP1 expression levels were increased in tumor tissues compared with those of tumor-adjacent tissues from the same CRC patients." (PMID 33384962, 2020). "Immune subsets were characterized for CD4, CD8, FOXP3, CD20, CD33, and PD1 using immuno-fluorescence staining in stroma, tumor, and combined stroma and tumor tissue." (PMID 32150594, 2020). "Using immunohistochemistry, tumor tissues were stained with antibodies against CD3, CD8, CD163, iNOS, Forkhead box P3 (FOXP3), and CD33." (PMID 30729718, 2019). "Those cells are now known as granulocytic MDSC, or PMN-MDSC (CD11b+HLA-DR−/low CD33+ CD15+ CD14−), one of several subpopulations of MDSC responsible for profound suppression of anti-tumor immunity and failure of anti-tumor immunotherapy." (PMID 31275327, 2019). "Tumor-derived TGF-β stimulated CD39 and CD73 expression in CD11b+CD33+ MDSC in tumor tissues and peripheral blood of NSCLC patients, thereby inhibiting activity of T cells and NK cells and protecting tumor cells from the cytotoxic effect of chemotherapy." (PMID 31024543, 2019). "These antibody-targetable cell surface membrane proteins include CD22, CD25, CD30, CD33, CD123, and FcεRI, which have all been found in tumor MC from SM patients." (PMID 30696068, 2019). "The infiltration of Foxp3+ T cells and CD33+ MDSC into the tumor nest was rare, thus we calculated the densities of these cells in total tumor area." (PMID 30285868, 2018). "MM tumor cells were purified using the Rosette Step MM purification kit, which removes other contaminating hematopoietic cells that contain CD2, CD14, CD33, CD41, CD45RA, CD66b markers and glycophorin A on red blood cells (RBCs)." (PMID 30383785, 2018). "On co-incubation day 5, and again at the end of incubation period on day 11, cell cultures were harvested and stained with CD33 and CD3 antibodies in order to identify HL-60 tumor cells and CAR T cells respectively." (PMID 30524966, 2018). "We characterized the expression of PD-L1 in tumor and TAICs, and evaluated the density of TAICs expressing CD4, CD8, and CD33 on sequential whole tumor sections from resected stage II-IV LADCs." (PMID 30216999, 2018). "Here, we report on the robust anti-tumor activity of a compound CAR (cCAR) T-cell possessing discrete scFv domains targeting two different AML antigens, CD123, and CD33, simultaneously." (PMID 29515236, 2018). "At last, one tumor characteristic (TNM stage) and four immune variables (CD8, Foxp3, CD33, PD-L1-TC) had independent prognostic value for the OS of ESCC patients." (PMID 30285868, 2018). "Here, we found that tumor LMP1 expression is correlated with glucose transporter 1 (GLUT1) levels, CD33+ MDSC number and unfavorable survival in patients with NPC." (PMID 28732079, 2017). "It includes antibodies directed against tumor cells belonging to the hematopoietic lineage, lymphocytes (CD20, CD52, CD38, etc.), and myeloid cells (CD30, CD33, etc.)." (PMID 28855903, 2017). "Surprisingly, HLA-DRlo cells represented a minority (∼15%) of the CD14+ monocyte population within the tumour specimen itself, with the majority of monocyte lineage cells displaying surface markers consistent with traditional monocytes (CD14+CD33+HLA-DRhi)." (PMID 28146145, 2017).
tumor (continued). "Anti-CD33- and anti-CD123-CD28ζ-EGFRt cells have been designed that can be eliminated by cetuximab if either CRS or any on-target/off-tumor toxicities are observed." (PMID 28851445, 2017). "It is unclear whether targeting CD33 with a CAR would result in hepatic toxicity as seen with GO, however, considering that administration of CAR T-cells has been associated with cytokine release syndrome and other potential off-tumor effects in patients, safety measures are here investigated." (PMID 27907031, 2016). "Further, other tumor antigens, such as CS1, CEA, CD138, and CD33, are targeted by CARs expressed by NK cells, although NK-92, YT, or NKL cell lines were used." (PMID 26089823, 2015). "Considering the mean quantile of expression versus other probes, surface markers CD64, CD1D, CD14, CD33, CD8A, CD16b, CD45 maintain a low level in cell lines versus microdissected tumor (all lower than the 35th quantile, p)." (PMID 25380171, 2014). "The cutoff value for the density of CD8, CD20, and CD33+/p-STAT1+ groups was 28, 34, and 11 cells, respectively, per high-powered field in the center of the tumor." (PMID 23307253, 2013). "Previously identified as transcriptional regulators in some murine tumor-derived MDSC subsets, we now show that these transcription factors are elevated in human MDSC and, importantly, are differentially expressed in CD33+ versus CD11b+ MDSC subsets." (PMID 21658270, 2011). "When transduced into T cells, My96-28z CAR-T cells exhibited significantly enhanced cytotoxicity compared with mock-transduced non-CAR T cells against CD33-expressing tumor cell lines co-cultured for 48 h." (PMID 40248694, 2025). "Additionally, CD33+CD14− PMN‐MDSC levels increased in patients with larger tumors, whereas CD11b+CD14+/CD33+CD14+ M‐MDSC levels decreased in those with lymphatic tumor emboli." (PMID 39749673, 2025). "Increased proportions of postoperative CD33+CD14+ cells relative to preoperative levels were evident in patients without lymphatic tumor emboli." (PMID 39749673, 2025). "We also examined the expression of CD38, CD33, and CXCR2 in tumor tissues of TE10 tumor-bearing hu-HSC-NOG-EXL mice treated with AZD4547 10 mg/kg for 21 d and AZD4547 treatment significantly reduced the CD38, CD33, and CXCR2 levels in tumor tissues." (PMID 40722739, 2025). "In addition, IGV visualization confirmed significant enrichment of eccDNA at genomic loci of tumor-related genes such as FLT3, RUNX1, CD33, and HMGB1." (PMID 41278279, 2025). "However, similar therapeutics in AML thus far remain of limited utility as all leading targets (CD33, CD123, CLL-1) have significant expression on normal hematopoietic and/or endothelial cells, leading to “on target, off tumor” toxicity concerns." (PMID 41282197, 2025). "Consistent with these mechanistic insights, clinical analyses revealed that elevated levels of SAA1, IL1B, and CD33+ MDSCs were significantly correlated with poorer overall survival in EOC patients, underscoring the SAA1/IL-1β/MDSC axis as a key driver of tumor progression and adverse prognosis." (PMID 41029721, 2025). "Post-treatment analyses showed that compared to non-treated tumor cells, the tumor cells remaining after CAR33-T cell treatment were CD33-negative/low and exhibited elevated levels of CSC markers such as SOX2 and OCT3/4." (PMID 39893165, 2025). "They achieved around 30%–60% of transduction rates, and CD33 CAR-NK efficiently eliminated OCI-AML2 and primary AML cells in vitro, even at low effector:target ratios, and they were able to kill tumor cells in rechallenge experiments after 3 rounds of repeated antigen stimulation." (PMID 38694825, 2024). "Results from a pioneer study showed that combining anti-CD33 CAR-DC with anti-CD33 CAR-T cells enhanced CAR-T cell function and cytotoxicity compared to the results obtained with CAR-T cells alone, resulting in improved tumor control in AML xenograft mouse models." (PMID 38904025, 2024).